DHPS (deoxyhypusine synthase)
Description:
Catalyzes the NAD-dependent oxidative cleavage of spermidine and the subsequent transfer of the butylamine moiety of spermidine to the epsilon-amino group of a critical lysine residue of the eIF-5A precursor protein to form the intermediate deoxyhypusine residue. This is the first step of the post-translational modification of that lysine into an unusual amino acid residue named hypusine. Hypusination is unique to mature eIF-5A factor and is essential for its function.
Synonyms: DHS; DS; MIG13; NEDSSWI
Tractability: Small molecule: a structure with a bound ligand is known; a high-quality ligand is known. PROTAC: ubiquitination databases record sites on it; its protein half-life has been measured; a small molecule that binds it is known.
Target class: Enzyme; Transferase
Gene: Protein-coding gene on chromosome 19 (12,673,411 to 12,681,894, reverse strand). Ensembl gene ENSG00000095059.
Subcellular location (Human Protein Atlas): Cytosol; Nucleoplasm
Pathways (Reactome):
Metabolism of proteins: Hypusine synthesis from eIF5A-lysine
Gene Ontology:
Molecular function: deoxyhypusine synthase activity; identical protein binding; protein binding
Biological process: protein maturation; spermidine metabolic process; positive regulation of cell population proliferation; translation; peptidyl-lysine modification to peptidyl-hypusine; spermidine catabolic process
Cellular component: cytoplasm; cytosol
Genetic constraint (gnomAD): Loss-of-function variants: 25 observed, 42.38 expected, observed/expected ratio (o/e) 0.59, 90% interval 0.43 to 0.82. The upper end of that interval is the gene's LOEUF score, 0.82, which puts it in group 3 of 6, group 1 being the genes least tolerant of losing a copy. Missense variants: 510 observed, 524.07 expected, observed/expected ratio (o/e) 0.97, 90% interval 0.9 to 1.05. Synonymous variants: 250 observed, 215.9 expected, observed/expected ratio (o/e) 1.16, 90% interval 1.04 to 1.29.
Homologues: Orthologues: chimpanzee DHPS (99% identical), macaque DHPS (98% identical), pig DHPS (95% identical), dog DHPS (95% identical), rabbit DHPS (94% identical), rat Dhps (92% identical), mouse Dhps (91% identical), guinea pig DHPS (90% identical), zebrafish dhps (76% identical), tropical clawed frog dhps (71% identical), Drosophila melanogaster Dhps (61% identical), Caenorhabditis elegans dhps-1 (58% identical).
Diseases named in the same sentence as DHPS in open-access papers:
DHPS is named in the same sentence as 41 diseases in open-access papers, as found by Europe PMC text mining. Sharing a sentence is not in itself a finding about the gene and the disease. The quoted sentences say what the papers report.
developmental delay (5 papers, 2021 to 2026). "Patients with DHPS deficiency typically present with global developmental delays, intellectual disabilities, speech and motor impairments, seizures, and various dysmorphic features." (PMID 42239796, 2026). "Rare biallelic pathogenic variants in DHPS have been included global developmental delay, intellectual disability, and seizures." (PMID 34273022, 2022). "In 2019, it was shown that polyamine metabolite processing disrupted by loss-of-function variants in deoxyhypusine synthase (DHPS) is also associated with global developmental delay and multiple neurological phenotypes." (PMID 33806076, 2021). "The patients carrying biallelic DHPS variants, or heterozygous EIF5A variants, share common phenotypes including intellectual disability and developmental delay." (PMID 34688659, 2021). "The three proteins eIF5A1, DHPS, and DOHH are highly conserved in eukaryotes and their pathogenic variants are collectively referred to as eIF5A1 and hypusination-related disorders that are characterized by global developmental delay, intellectual disability, facial dysmorphism, and microcephaly." (PMID 36848144, 2023).
diabetes (5 papers, 2020 to 2023). "Overcoming this challenge is crucial, as examining the tissue-specific loss of DHPS and eIF5A will be important in distinguishing the effects of eIF5A hypusination in each distinct cell type involved in diabetes pathogenesis." (PMID 35448531, 2022). "A recent study of adipose tissue macrophages, which are instrumental in the progression of obesity-induced diabetes, found that these cells expressed more eIF5Ahyp and exhibited enhanced DHPS activity in obese mice compared to control mice." (PMID 35448531, 2022). "Our work and that of others suggest a role for eIF5AHyp and DHPS in promoting T cell and B cell proliferation, which was the basis for our hypothesis that perhaps eIF5AHyp is differentially expressed in immune cells in individuals with diabetes compared with controls." (PMID 32208453, 2020). "In mice, β cell–selective deletion of deoxyhypusine synthase, which is normally present in higher amounts in HFD-fed WT mice, attenuates HFD-induced β cell proliferation, resulting in smaller islets and the development of diabetes." (PMID 38099492, 2023).
melanoma (4 papers, 2021 to 2026). A malignant, usually aggressive tumor composed of atypical, neoplastic melanocytes. "This review synthesizes cutting-edge insights into the deoxyhypusine synthase (DHPS)/eukaryotic initiation factor 5A (eIF5A) hypusination circuit as a critical amplifier of oncogenic signaling in melanoma." (PMID 42072695, 2026). "Based on the new mechanism of DHPS regulation in melanoma, the target potential of DHPS has been identified, which makes the development of DHPS‐targeted inhibitors of great significance." (PMID 38952061, 2024). "In conclusion, this study has innovatively identified DHPS‐mediated m6A methylation modification in melanoma and obtained a novel DHPS allosteric inhibitor, GL‐1, which had high efficiency, low toxicity, and good bioavailability in vivo and in vitro." (PMID 38952061, 2024). "In this study, mRNA‐seq analysis showed that the number of genes up‐regulated by mRNA expression after DHPS knockdown was higher than the number of genes down‐regulated, suggesting that DHPS is closely related to the mRNA stability in melanoma cells." (PMID 38952061, 2024). "The screening of the hit compound (GL‐1) at the enzyme and cellular levels, in vivo studies were conducted to determine the ability of GL‐1 to target DHPS and its efficacy against melanoma." (PMID 38952061, 2024). "In contrast, MeRIP‐seq results showed that the number of genes down‐regulated by m6A after DHPS knockdown was lower than that of control in melanoma cells." (PMID 38952061, 2024). "Multi‐omics studies have revealed that DHPS regulates m6A modification and maintains mRNA stability in melanoma cells." (PMID 38952061, 2024). "The mechanism by which deoxyhypusine synthase (DHPS) promotes melanoma development remains elucidated." (PMID 38952061, 2024). "Therefore, our results suggest that DHPS is a promising anti‐melanoma target that regulates intracellular m6A‐methylation modification and influences protein translation." (PMID 38952061, 2024). "When the DHPS gene was knocked down, the proliferation of melanoma cells was inhibited." (PMID 38952061, 2024). "It was found that DHPS is more highly expressed in melanoma than in normal skin tissue." (PMID 38952061, 2024). "Additionally, western blot analysis revealed that the expression of three vital proteins that regulate m6A modification, namely METTL3, YTHDF2, and YTHDC1, was reduced in melanoma cells after DHPS knockdown." (PMID 38952061, 2024). "Here, we aimed to uncover the pro‐oncogenic mechanism of DHPS in melanoma by mediating the hypusination of eIF5A to promote the m6A modification of METTL3 itself through a multi‐omics approach to elucidate the value of DHPS as a therapeutic target for melanoma." (PMID 38952061, 2024). "Meanwhile, the effect of DHPS inhibitors on Cu2+ homeostasis in melanoma cells was found in the study of the anticancer mechanism of GL‐1, and DHPS may be involved in the metabolic regulation of melanoma cells." (PMID 38952061, 2024). "In this study, we demonstrate in the BRAFV600E melanoma cells A375 and SK-MEL-28 that DHPS knockdown induces growth arrest associated with p21CIP1 upregulation whereas eIF5A knockdown induces cell death, and that p21CIP1 knockdown can switch the growth arrest induced by DHPS knockdown to cell death." (PMID 34947982, 2021). "Key molecular targets in this process, including ODC1, AMD1, DHPS and c-Myc could serve as effective drug targets addressing specific vulnerabilities in BRAFi resistant melanoma, warranting development of novel breakthrough therapies against therapy resistant melanoma." (PMID 38965534, 2024). "Taken together, these results suggest that DHPS mediates the hypusination of eIF5A by assisting METTL3 in recognizing its m6A site for methylation modification and maintaining the stability of mRNAs in melanoma cells." (PMID 38952061, 2024).
melanoma (continued). "Finally, we propose a paradigm shift: targeting the DHPS/eIF5A axis represents a strategy to disrupt the "non-oncogene addiction" of melanoma-its reliance on hyperactive translation and adaptive survival mechanisms-offering a promising avenue alongside targeted therapies and immunotherapies." (PMID 42072695, 2026). "Here we demonstrate that DHPS has a role independent of eIF5A hypusination in A375 and SK-MEL-28 human melanoma cells, in which the extracellular signal regulated kinase 1/2 (ERK1/2) pathway is deregulated." (PMID 34947982, 2021). "Subsequent studies revealed that METTL3 could not regulate the expression of YTHDC1/YTHDF2 proteins in melanoma, which also predicts that the methylation modifications regulated by METTL3 are not required for all genes, but that METTL3‐mediated m6A‐methylation modification is dependent on DHPS." (PMID 38952061, 2024).
malaria (3 papers, 2015 to 2021). Malaria is a serious and sometimes fatal disease caused by a parasite that commonly infects a certain type of mosquito which feeds on humans. "It was shown that pharmacological inhibition of the enzymes involved in this pathway, deoxyhypusine synthase (DHS) and the deoxyhypusine hydroxylase (DOHH), arrested the growth of malaria parasites." (PMID 27516964, 2016).
neuroblastoma (3 papers, 2020 to 2021). Neuroblastoma (NB) is the most common solid, extracranial childhood tumor. "The augmented expression of DHPS was reported to correlate with poor prognosis in several tumor types, such as neuroblastoma and esophageal squamous cell carcinoma." (PMID 32989218, 2020). "The spermidine and deoxyhypusine synthase (DHPS) inhibitor, GC7, inhibits activation of EIF5A and induces apoptosis of neuroblastoma cells via the regulation of the p21/Rb signaling axis." (PMID 33996900, 2021).
AIDS (2 papers, 2020 to 2021). A syndrome resulting from the acquired deficiency of cellular immunity caused by the human immunodeficiency virus (HIV). "Recently, the presence of DHPS mutation at codon 55 was recently observed in one out of 60 AIDS-related PcP patients in China, and a prevalence of 1.5% of DHPS mutations has been reported among hospitalized patients from Turkey." (PMID 34682277, 2021). "The overall rate of DHPS gene mutations was 7.1% among AIDS-related PcP patients in Harare, Zimbabwe." (PMID 34682277, 2021). "These indicated that the prevalence of DHPS mutations in P. jirovecii isolates in AIDS-PCP patients in the region was low." (PMID 32911508, 2020). "In conclusion, our study showed that atypical mutations at codons 55 and 57 in the P. jirovecii DHPS gene were low for AIDS-PCP patients in a low endemic area in China." (PMID 32911508, 2020). "However, a few years later, in the same geographical area in South Africa, a prevalence of 56% of DHPS mutations was reported in adult AIDS-related PcP patients." (PMID 34682277, 2021). "The DHPS gene of 147 HIV/AIDS patients was detected, and 60 cases were positive." (PMID 32911508, 2020). "A study of relapsed PcP in AIDS patients suggests that DHPS mutations can be selected de novo within patients by the pressure of a sulfa or sulfone drug and that DHPS mutations may be associated with reactivation of a silent P. jirovecii infection." (PMID 34682277, 2021).
atherosclerosis (2 papers, 2021 to 2024). A disease characterized by the build-up of fatty material and calcium deposition in the arterial wall resulting in partial or complete occlusion of the arterial lumen. "DHPS, reported as an atherosclerosis marker, was also expressed in smooth muscle cells." (PMID 34103026, 2021).
gastritis (2 papers, 2020 to 2025). Inflammation of the stomach. "In this report, we showed that patients with H. pylori gastritis exhibit increased level of DHPS and hypusinated EIF5A." (PMID 41282235, 2025). "We found that these infected mice develop less gastritis, demonstrating that the activity of DHPS in GECs supports stomach inflammation." (PMID 41282235, 2025). "Interestingly, when we specifically knocked-down DHPS in intestinal epithelial cells, we found less H. pylori-induced gastritis in the stomach, suggesting that hypusination in GECs supports inflammation." (PMID 41282235, 2025). "To determine whether DHPS is expressed in gastric macrophages in humans, we assessed gastric biopsies from uninfected individuals and H. pylori-infected patients with gastritis." (PMID 33326776, 2020).
glioblastoma (2 papers, 2012 to 2024). The most malignant astrocytic tumor (WHO grade IV). "Here we report that eIF-5A as well as the hypusine-forming enzymes deoxyhypusine synthase (DHS) and deoxyhypusine hydroxylase (DOHH) are highly overexpressed in glioblastoma patient samples." (PMID 22927971, 2012). "Moreover, EIF5A, DHPS, and DOHH are also highly expressed in glioblastoma (GBM), the most aggressive primary brain tumor in adults with a poor prognosis (a 5-year survival: ~5%)." (PMID 39125743, 2024).
lung adenocarcinoma (2 papers, 2020 to 2022). A carcinoma that arises from the lung and is characterized by the presence of malignant glandular epithelial cells. "In this study, we found that higher DHPS expression levels were associated with poor prognosis in lung adenocarcinoma, which suggests that DHPS can be used as a marker for cancer prognosis." (PMID 32989218, 2020). "We found that higher expression of DHPS also correlated with poor survival in patients with lung adenocarcinoma." (PMID 32989218, 2020). "Moreover, we found that higher DHPS expression correlated with poor prognosis in lung adenocarcinoma and increased resistance to inhibitors of the ERK1/2 pathway." (PMID 32989218, 2020).
lung carcinoma (2 papers, 2020 to 2021). "As a pair of protein-coding cis-sense/antisense transcripts, WDR83 and DHPS are upregulated simultaneously and correlate positively in lung cancer." (PMID 35126467, 2021). "The lung cancer cell lines with higher DHPS protein levels showed higher hypusination levels of eIF5A and are more resistant to these inhibitors." (PMID 32989218, 2020). "To determine whether drug sensitivity was correlated with DHPS expression levels, we analyzed the Genomics of Drug Sensitivity in Cancer datasets of lung cancer cells." (PMID 32989218, 2020).
microcephaly (2 papers, 2022 to 2023). A congenital or acquired developmental disorder in which the circumference of the head is smaller than normal for the person's age and sex. "Rare biallelic loss of function variants in DOHH were identified in an 8 year old girl presenting a severe neurodevelopmental disorder with several symptoms such as hypotonia, dysmorphic features, and microcephaly, overlapping with those found in DHPS and EIF5A-related disorders." (PMID 34273022, 2022).
HIV-1 infection (1 paper, 2023). The type species of lentivirus and the etiologic agent of acquired immunodeficiency syndrome (AIDS). "To corroborate the effect of polyamines and EIF5A hypusination independent of HIV-1 infection, we added exogenous putrescine hydrochloride, spermidine, and GC7, a DHPS inhibitor." (PMID 36693889, 2023).
ischemic stroke (1 paper, 2018). A stroke disorder caused by obstruction of blood flow to the brain, due to thrombotic (local blood clot formation) or embolic (due to a blood clot or other material traveling from another site) event. "We have screened autoantibody levels in the sera of patients with ischemic stroke and report TUBB2C, ATP2B4, BMP-1, DHPS, and SH3BP5 as possible antigens that may be implicated in the development of stroke." (PMID 29507658, 2018).
latent infection (1 paper, 2022). "We observed multiple genes in polyamine pathway, including ODC1, SRM, SMS and DHPS, were significantly dysregulated due to KSHV latent infection." (PMID 35486659, 2022).
lymphoma (1 paper, 2022). A malignant (clonal) proliferation of B- lymphocytes or T- lymphocytes which involves the lymph nodes, bone marrow and/or extranodal sites. "In addition, KSHV latency-associated increase of DHPS gene expression was further validated in all three tested KSHV-positive lymphoma cell lines (TREx BCBL1-RTA, BCBL1, BC-3) at both mRNA and protein levels." (PMID 35486659, 2022).
myocardial ischemia (1 paper, 2015). A disorder of cardiac function caused by insufficient blood flow to the muscle tissue of the heart. "Next, we analyzed the effects of N1-guanyl-1,7-diaminoheptane (GC7), a hypusination inhibitor that blocks deoxyhypusine synthase (DHS) function, and the anti-eIF5A neutralizing mAbs in a rat model of myocardial ischemia/reperfusion." (PMID 26348594, 2015).
parasitemia (1 paper, 2020). "Collectively, these observations suggested that differences among patterns of DHFR and DHPS mutations within our volunteer population were not due to marked underlying differences in COI or parasitemia." (PMID 33324580, 2020).
Pneumocystis infection (1 paper, 2023). "Although no mutations at codons 55 and 57 were detected during the study of the DHPS gene, six patients enrolled in the current study (P9, P10, P11, P12, P13, and P15) had a fatal outcome, with Pneumocystis infection as a leading cause of death." (PMID 38069248, 2023).
rheumatoid arthritis (1 paper, 2021). A chronic, systemic autoimmune disorder characterized by inflammation in the synovial membranes and articular surfaces. "The folate biosynthesis (ko00790) is an attractive pathway for the development of new therapies against some human diseases, including cancer and rheumatoid arthritis, which involves several steps and many enzymes, such as GTPCHI, DHNP, DHPS, and DHFR." (PMID 34604366, 2021).
cancer (8 papers, 2020 to 2024). A tumor composed of atypical neoplastic, often pleomorphic cells that invade other tissues. "An in vitro activity assay was developed to characterize the activity of deoxyhypusine synthase, a highly promiscuous enzyme that is essential for cell proliferation and viability in eukaryotes and a promising therapeutic target to treat cancer." (PMID 33247548, 2021). "In various human cancer cell lines, the inhibitors of deoxyhypusine synthase (DHS) and deoxyhypusine hydroxylase were found to be involved in the formation of hypusine, and played a vital role in the antiproliferative effects." (PMID 34039408, 2021). "Deoxyhypusine synthase with its central function in eukaryotic organisms has long been a topic of biochemical research and has also come into prominence for drug development in the treatment of cancer and other diseases." (PMID 33247548, 2021). "On the other hand, DHPS expression appeared to correlate positively with sensitivity to other agents, such as NAMPT, BCL2, and MDMX inhibitors, indicating that DHPS level can be used as a predictive biomarker for response to several different anti-cancer agents." (PMID 32989218, 2020). "Interfering with hypusination of eIF5A with GC7, an inhibitor of deoxyhypusine synthase (DHPS), could be a potential approach that could affect cancer cells with a high rate of protein synthesis." (PMID 32151059, 2020).